TMPRSS2 (transmembrane serine protease 2)
Diseases named in the same sentence as TMPRSS2 in open-access papers (continued):
Sharing a sentence is not in itself a finding about the gene and the disease.
prostate carcinoma (continued). "Because TMPRSS2 is regulated in the prostate by androgens, it was proposed that this gene rearrangement could be a mechanism whereby the ETV1 or ERG oncogenes were overexpressed, leading to prostate cancer." (PMID 18781147, 2008). "However, two cohort studies of men with clinically localised prostate cancer who did not undergo treatment (i.e. watchful waiting) showed that men who had TMPRSS2:ERG fusion had lower prostate cancer-specific survival compared to men without fusion expression." (PMID 17971772, 2007). "Thus, a CYP24A1 resistant VDR agonist may be beneficial for treatment of TMPRSS2:ERG positive prostate cancer; one negative consequence of TMPRSS2:ERG expression is inactivation of VDR signaling." (PMID 28591703, 2017). "In view of the role of fusion protein TMPRSS2-ERG in prostate cancer and to expand our previous studies on the transcriptional regulation of the IGF1R gene, we examined the hypothesis that the IGF1R gene constitutes a novel downstream target for the TMPRSS2-ERG prostate-specific chimera." (PMID 27285981, 2016). "In this study, we hypothesize that multiple TMPRSS2:ERG fusion subtypes and additional low-prevalent TMPRSS2:ETS fusion genes are collectively more informative than any single marker alone in the noninvasive detection and stratification of clinically significant prostate cancer." (PMID 24133629, 2013). "Conversely, prostate cancer patients without the TMPRSS2–ERG fusion gene may be better suited for therapies that target IGFs and Jak-Stat signalling, in which IGF signalling can be targeted through the use of tyrosine kinase inhibitors or monoclonal antibodies." (PMID 20068566, 2010). "Conversely, TMPRSS2–ERG, a prostate cancer fusion gene, can be induced in prostate cells, but not in endometrial cells (lane 6 vs. 2)." (PMID 34928964, 2021). "Case 11 harbored a TMPRSS2‐ERG fusion, an oncogenic fusion common in prostate cancers without any reported occurrences in lung cancer." (PMID 32191822, 2021). "The vast majority of cancers are heterogeneous for TMPRSS2:ERG fusions on a patient level, challenging the concept of classifying prostate cancer patients into “fusion type” and “non-fusion type” prostate cancer." (PMID 27530104, 2016). "SENP1 immunostaining was slightly more frequent in TMPRSS2:ERG rearranged and ERG positive prostate cancers than in ERG negative tumors." (PMID 26202067, 2015). "Over-expression of SPINK1 has been described in cancers lacking the TMPRSS2-ERG fusion and has been reported to identify a subset (approximately 5–10%) of prostate cancers that behave more aggressively." (PMID 26172920, 2015). "Rearrangements involving androgen-regulated TMPRSS2 and ETS family members (ERG, RTV1, ETV4) were detected in nearly half of the prostate cancers but none of the benign prostate tissues that were tested." (PMID 24499728, 2014). "In the next section we will briefly discuss difference of TMPRSS2-ERG positive and negative prostate cancer cells and how gene networks are regulated in fusion positive cancer cells." (PMID 24739220, 2014). "At the genomic level, studies using large clinical cohorts demonstrated both presence and absence of enrichment between TMPRSS2:ERG fusion and PTEN gene deletion in prostate cancer." (PMID 24098661, 2013). "Furthermore, the TMPRSS2–ERG fusion may have an important prognostic and predictive value, because of which differentially regulated mRNAs (most notably ERG) in repeated experiments suggest that targeted therapy in prostate cancer could be aided by this biomarker." (PMID 20068566, 2010).
prostate carcinoma (continued). "Cases in this study were population-based unlike several previous TMPRSS2-ERG studies, there was a mean surveillance period of 11.6 years after diagnosis, and prostate cancer-specific death was confirmed by death certificate." (PMID 18694509, 2008). "We examined TMPRSS2 immunohistochemical expression in lung tissue from 20 consecutive autopsy cases of men with prostate cancer (6 receiving ADT at time of death), compared with non-ADT prostate cancer patients and age-matched women controls." (PMID 41150771, 2025). "TMPRSS2-ERG fusions are not detected in the normal prostate epithelium or in benign prostatic hyperplasia but are found in premalignant prostatic intraepithelial neoplasia (PIN) lesions, suggesting a role in the early stages of prostate cancer development." (PMID 35267426, 2022). "Given the status of TMRSS2-ERG as the most relevant genomic fusion event so far identified in prostate cancer, we tested the expression of PDE4D7 in 1106 patients with (Primary PCa, TMPRSS2-ERG positive) and without (Primary PCa, TMPRSS2-ERG negative) this gene fusion." (PMID 26575822, 2015). "We found the TMPRSS2-ERG fusion in NCI-H660, but not in any other prostate cancer cell line." (PMID 23341502, 2013). "Genes with significant differential expression between the TMPRSS2-ERG positive and negative lesions were identified and validated by qRT-PCR in a larger series of prostate carcinomas, as well as by immunohistochemistry and chromatin immunoprecipitation analyses (ChIP)." (PMID 21814574, 2011). "Therefore, we investigated PSMA regulation in TMPRSS2-ERG fusion-positive VCaP and fusion-negative LNCaP prostate cancer cells." (PMID 21731703, 2011). "The TMPRSS2:ERG fusion gene is not present in non-neoplastic prostate epithelium, but has been described in high-grade prostatic intraepithelial neoplasia (HGPIN) lesions, suggesting that it might represent an early event in the development of prostate cancer." (PMID 33634124, 2021). "Several subsequent studies have suggested that the TMPRSS2-ERG fusion protein is not only present in late stage prostate cancer but in benign prostatic hyperplasia (BPH), high-grade prostate intra-epithelial neoplasia (HGPIN) and even in non-malignant tissue adjacent to prostate cancer foci." (PMID 18694509, 2008).
viral infection (270 papers, 2012 to 2026). "Genetic studies have revealed quantitative trait loci (eQTLs) associated with TMPRSS2 expression, revealing differences in sensitivity to viral infections among groups." (PMID 40297833, 2025). "Sex hormones regulate the expression of the viral receptors ACE2 and TMPRSS2, which affect the extent of viral infection and consequently cause variable outcomes." (PMID 38923119, 2024). "Concomitant expression of ACE2, TMPRSS2, and/or furin was especially increased in these cell subsets, suggesting a higher susceptibility for viral infection." (PMID 38381158, 2024). "The protease produced by the transmembrane serine protease 2 (TMPRSS2) gene enhances viral infections and has been linked to severe acute respiratory syndrome coronavirus 2 pathogenesis." (PMID 36457338, 2022). "Several studies on the genetic contribution of TMPRSS2 polymorphisms (rs35074065, rs12329760) to individual susceptibility to viral infection either confirmed or disconfirmed this correlation." (PMID 36012436, 2022). "ACE2 and TMPRSS2 are associated with viral cell entry, and are involved in binding of the spike protein and the beginning of viral infection." (PMID 36171597, 2022). "We investigated the ACE2 and TMPRSS2 expression levels of cell types from 31 organs to evaluate the risk of viral infection using single-cell RNA sequencing (scRNA-seq) data." (PMID 33401657, 2021). "A549 cells were chosen as a cell model, since they derive from the lung, the natural site of SARS-CoV-2 infection, express ACE2 and TMPRSS2 protein required for the virus entry, and are also susceptible to the virus infection." (PMID 34163530, 2021). "In a recent single-cell transcriptomic study, ACE2 and TMPRSS2 were co-expressed in lung, esophagus, ileum, and colon cells, suggesting the possibility of direct viral infection in the digestive system, thereby causing GI symptoms." (PMID 34722595, 2021). "The protease encoded by the TMPRSS2 gene facilitates viral infections and has been implicated in the pathogenesis of SARS-CoV-2." (PMID 33921689, 2021). "Additionally, emerging research has linked TMPRSS2 to the pathogenesis of ulcerative colitis, expanding its relevance beyond viral infections." (PMID 39858469, 2025). "Furthermore, these cells will be an essential tool to investigate other zoonotic viral diseases caused by TMPRSS2-dependent viruses." (PMID 38251326, 2023). "ACE2 and TMPRSS2 are expressed in multiple tissues, including lung, kidneys, small intestine, colon, brain, heart, liver, and blood vessels, making these tissues susceptible to viral infection." (PMID 38002267, 2023). "The main hydrolase implicated in the viral infection process is TMPRSS2." (PMID 36291025, 2022). "Given the significance of RG4 on TMPRSS2 regulation and virus infection, we hypothesized that TMPRSS2 upregulation in susceptible cells at the site of infection may contribute to SARS-CoV-2 pathogenesis." (PMID 35301316, 2022). "Although whether the activities of ACE2 and TMPRSS2 on the tongue are associated with virus infection is unclear, taste impairment has been recognized as a symptom of COVID-19." (PMID 34534255, 2021). "The combination of arbidol with chloroquine could more efficiently inhibit viral infection through endocytic pathway in TMPRSS2-deficient Vero-E6 cells." (PMID 33750821, 2021). "This suggests that a subpopulation of liver epithelial cells expresses machinery for both SARS-CoV-2 entry (ACE2) and priming (TMPRSS2) and might be susceptible to viral infection leading to liver dysfunction." (PMID 33968947, 2021). "In fact, ACE2 and TMPRSS2 exhibit high mRNA expression in thethyroid in both sexes; the first case ofsubacute thyroiditis (a thyroid dysfunction due to a viral infection or a postviralinflammation of the thyroid) associated with SARS-CoV-2 infection was reported in a youngItalian woman." (PMID 32652001, 2020).
viral infection (continued). "Due to the acute role of TMPRSS2 as a host cell factor for viral infections, serine protease inhibitors (Camostat, Nafamostat, and Leupeptin) have been implicated in the antiviral therapeutic strategy targeting TMPRSS2 with high antiviral activities." (PMID 32764454, 2020). "The high levels of expression of ACE2 and TMPRSS2 in mucin secreting goblet cells of the nasal passages and their susceptibility to viral infection, suggests that similar goblet cells that also exist in the conjunctiva might also be susceptible to infection." (PMID 32883010, 2020). "In addition, the infectivity of the SARS-CoV-2 Delta variant, which utilizes both TMPRSS2-mediated and cathepsin-mediated membrane fusion for viral infection, could be lowered by inhibitors of either pathway." (PMID 37990007, 2023). "While these results suggest potential activation of the host protease TMPRSS2 by HDACIs, this might be irrelevant to the risk of viral infection considering that TMPRSS2 is involved in the process of viral entry only after the virus has bound to ACE2 on epithelial cells." (PMID 33564039, 2021). "TMPRSS2 plays a critical role in viral infection by cleaving S protein at both the S1/S2 boundary and the S2′ site, exposing the fusion peptide." (PMID 40297833, 2025). "Downregulating TMPRSS2 expression via diverse methods provides alternate approaches to fighting viral infections." (PMID 40297833, 2025). "A combination therapy that suppresses TMPRSS2 and furin has shown a substantial decrease in viral infection, with particular combinations attaining up to a 95% drop in lung cells." (PMID 40297833, 2025). "The process of viral entry into the host cells and the development of viral infections via membrane fusion by TMPRSS2 emphasizes the relevance of this protease in viral entry." (PMID 40297833, 2025). "This interaction of FH hinders the virus from binding to its cell surface receptors, resulting in a reduction in SARS-CoV-2 infection of A549 cells that express both human ACE2 and TMPRSS2, while FP enhances the viral infection." (PMID 40895576, 2025). "Mechanistically, NET triggered by SARS-CoV-2 depends on angiotensin-converting enzyme 2 (ACE-2) and serine protease TMPRSS2, and active viral infection and/or replication is necessary to induce NET release." (PMID 41322987, 2025). "The expression of TMPRSS2 across multiple tissues, particularly in the intestinal and respiratory tracts, coincides with common locations of viral infection, indicating its function in viral transmission and pathogenesis." (PMID 40297833, 2025). "Animal studies show that TMPRSS2 deletion mice have less severe lung damage during viral infections, highlighting its potential as a therapeutic target." (PMID 40297833, 2025). "A continued study of the processes and expression characteristics of TMPRSS2 is critical for developing antiviral treatments and vaccines against viral infections of the respiratory tract." (PMID 40297833, 2025). "This review provides a summary of TMPRSS2 inhibitors currently under study, with some already in clinical trials to test their effectiveness against viral infections." (PMID 39858469, 2025). "TMPRSS2 is a type II transmembrane serine protease involved in the pathological process of numerous viral diseases, including coronaviruses like SARS-CoV-2, SARS-CoV, and MERS-CoV." (PMID 40297833, 2025). "TMPRSS2 is now recognized as a significant element in the infectivity and pathogenesis of many viral infections, making it essential to discover possible treatment strategies." (PMID 40297833, 2025). "This comparative investigation focuses on TMPRSS2 role in various viruses, demonstrating its major impact on viral infection and pathogenesis." (PMID 40297833, 2025). "Overall, transmembrane ACE2 and TMPRSS2 downregulation closely correlated with nucleocapsid production in infected cells and thus served as a valid marker for viral infection." (PMID 40431708, 2025).
viral infection (continued). "TMPRSS2 is localized to the plasma membrane, and co-opting of TMPRSS2 to enhance virus infection was initially described for influenza, where hemagglutinin cleavage for proteolytic activation was demonstrated." (PMID 40981424, 2025). "Structural insights highlight potential therapeutic targets against viral infections and cancers, leveraging TMPRSS2 interactions for drug development." (PMID 39565778, 2024). "TMPRSS2, a host enzyme essential for proteolytic activation and pathogenesis of coronaviruses, is a promising drug target for treating viral infections." (PMID 39003338, 2024). "In Caco-2 cells that equally allow cell entry through both the direct membrane fusion pathway and the endocytosis pathway, inhibition of TMPRSS2 using Camostat and inhibition of cathepsin-L using E-64d blocked viral infection of Caco-2 cells." (PMID 39443717, 2024). "Another cellular activation known to be associated with SARS-CoV-2 infection is the expression of transmembrane serine protease-2 (TMPRSS2), which acts as a significant determinant of the entry pathway for the virus; overexpression inhibits viral infection." (PMID 39304808, 2024). "Previous work demonstrated that high levels of TMPRSS2 correlate with strong viral infections because TMPRSS2 supports viral entry into the host cell." (PMID 38185627, 2024). "During viral infection, cell proteases such as TMPRSS2, utilized as a protein primer, activate the S protein by cleaving it into S1 and S2 subunits." (PMID 38226800, 2024). "The enzymatic activity of TMPRSS2 in viral infection and its inhibition have been proposed as novel mechanisms to reduce mortality associated with SARS-CoV-2 infection." (PMID 38601158, 2024). "This includes more efficient utilization of the factors that can facilitate virus infection and replication, such as transmembrane protease serine 2 (TMPRSS2), cathepsin, ADAM10, and ADAM17 proteases." (PMID 38399960, 2024). "CQ was found to have limited potency in inhibiting viral infection of human lung cells that express co-receptor TMPRSS2, such as Calu-3, which facilitates S protein priming and mediates viral entry via plasma membrane fusion instead of endocytosis." (PMID 36851716, 2023). "Another important target in combating SARS-CoV-2 is TMPRSS2, which contributes to viral infection and cell entry alongside the ACE2 receptor." (PMID 37809955, 2023). "It is not clear if this differential distribution was a result of downregulation in the expression of TMPRSS2 or a direct consequence of epithelial cell death due to viral infection." (PMID 38883409, 2023). "Recent investigations have discovered that the co-expression of ACE2 and TMPRSS2 in an organ is crucial for viral infection of that organ." (PMID 37426635, 2023). "Lastly, inhibition of the SARS-CoV-2 viral infection with short pre-treatment of cells with TMPRSS2 inhibitor Nafamostat resulted in complete inhibition of infection by the WT SARS-CoV-2 (p = 0.0038)." (PMID 38098019, 2023). "The findings of this study furtherconfirm the susceptibility of these brainstem nuclei to viral infection due to theexpression of ACE2R and TMPRSS2." (PMID 37172190, 2023). "The susceptibility of these cells to viral infection is associated with the co-expression of the ACE2 receptor and the co-receptor transmembrane protease serine 2 (TMPRSS2)." (PMID 37243127, 2023). "TMPRSS2 facilitates virus entry into host cells, making it a potential drug target for combating viral infections." (PMID 37660915, 2023). "When HEK293T cells were co-transfected with FXa, ACE2, and TMPRSS2 plasmids, FXa expression again blocked viral infection, showing a more pronounced effect during the early time points than without TMPRSS2." (PMID 37024459, 2023). "SARS-CoV-2 accesses cells via entry molecules, including ACE2, and infiltrates via proteolytic virus activation by host proteases, including TMPRSS2, which cleaves the S protein, resulting in viral infection and replication." (PMID 37563112, 2023).